SMAD4 (SMAD family member 4)
Diseases named in the same sentence as SMAD4 in open-access papers (continued):
Sharing a sentence is not in itself a finding about the gene and the disease.
cancer (continued). "In contrast, loss of DPC4 expression can be identified in 16% of invasive carcinomas arising from IPMN, suggesting that SMAD4 mutation is rather a late genetic change in pancreatic carcinogenesis in setting of IPMN." (PMID 24278753, 2012). "It was not surprising to find limited overlap of only 6 of 150 in IOSE, 6 of 92 in HaCaT, and 1 for all three studies in common with the 318 SMAD4 target genes in this study as only one, A2780, is a cancer cell line and the other two are normal cell lines." (PMID 21799915, 2011). "Based on immunohistochemistry analysis, positive staining for SMAD4 was mainly observed in the cytoplasm and to a lesser degree in the nuclei of cancer cells." (PMID 21791112, 2011). "In order to study the role of Smad4 in cancer, mouse models with Smad4 deletion specifically targeted to certain tissue types have been used." (PMID 22204491, 2011). "Loss of SMAD4 function facilitates EMT and its re-expression reverses the process in cancer cell lines." (PMID 21781349, 2011). "The information presented above suggests that Smad4-dependent and -independent signaling pathways regulate cancer cell resistance to chemotherapy." (PMID 20684793, 2010). "Promoter activities and TGFβ induction were assayed through transient transfections in Smad4-negative human cancer cells and their stable Smad4-positive derivatives." (PMID 18664273, 2008). "We are using gene transfer techniques to address functions of the tumor suppressor gene Smad4 in human cancer cells." (PMID 18664273, 2008). "Here, we present a review of the current state of the literature implicating the central Smad mediator, Smad4, in the development of cancer." (PMID 9862572, 1998). "Considering recent studies demonstrating enhanced efficacy of JAK/STAT inhibition with immunotherapy in cancer, Smad4-deleted PDAC may show increased sensitivity to this combination regimen." (PMID 39841099, 2025). "Hence, this study established LINC00909 as an important regulator of pluripotency factors, cancer stemness and metastasis by inhibiting SMAD4 expression." (PMID 40427100, 2025). "Notably, TGF-Beta pathway genes such as SMAD2, SMAD4, and TGFBR2 displayed differential mutation frequencies in all three cancers, suggesting a recurring pattern of dysregulation in this pathway among H/L patients." (PMID 40869017, 2025). "The initial discovery of SMAD4 deletion in PAAD has been extended to multiple cancer types." (PMID 39143229, 2025). "In addition, TRIM proteins (TRIM11/25/26/28/33/59/62/66/72) and TGFB pathways (Smad4 degradation) have been shown to promote epithelial–mesenchymal transition, cell migration, and invasion of cancer cells through activation of the TGF-β signaling pathway." (PMID 40338274, 2025). "Knockdown of UBE2D1 impairs cancer cell migration by reducing SMAD4 ubiquitination." (PMID 41208974, 2025). "Moreover, we expanded our investigation by performing a literature review to explore all molecularly characterized SMAD4 aberrant splicing variants associated with the JPS clinical phenotype and cancer susceptibility." (PMID 39063183, 2024). "While the involvement of STAT3 in cancer has been predominantly associated with chronic inflammation and fibrosis, our data underscore the significance of epistasis as a key factor that underlies functional antagonism between STAT3 and TGF-β/SMAD4 signaling." (PMID 38573819, 2024).
cancer (continued). "So far, 12 unique SMAD4 splicing variants, including those characterized in the present study, have been described in 24 patients with JPS or a personal and familial history of cancer." (PMID 39063183, 2024). "In cancer, SMAD4 inactivation is frequent, notably in over half of PDAC and various other cancers." (PMID 38666907, 2024). "This indicates that SMAD4 mutation alone is not sufficient to predispose cancer cells to a particular RAS phenotype." (PMID 38573819, 2024). "Notably, PARP1, a key protein in DNA damage repair and whose inhibitors are approved for various cancers, was previously shown to demonstrate enhanced interaction with SMAD4." (PMID 39528473, 2024). "This signaling cascade, facilitated by SMAD4, has the capacity to activate growth-inhibitory pathways in cancer cells, and upon binding to TGF-beta, SMAD complexes translocate to the nucleus, where they regulate the transcription of target genes responsible for cell cycle arrest and apoptosis." (PMID 39113194, 2024). "Cancer cell proliferation is inhibited by this TGFβ signaling, which requires functional SMAD4." (PMID 37377893, 2023). "In our study, given that circLDLRAD3 could negatively regulate the expression of miR‐558 and miR‐558 played a pro‐oncogenic role in cancer, we hypothesized that circLDLRAD3 might regulate the expression of its target gene Smad4 through regulating miR‐558." (PMID 37563869, 2023). "Additionally, TGFBR2, ACVR2A, and SMAD4 were shown to have high alteration frequencies in pan-cancer." (PMID 36968603, 2023). "Finally, one of the downstream of TGF-β/β-catenin is SMAD4, which is overexpressed in many types of cancer." (PMID 36912230, 2023). "The relevance of the remaining hub genes identified by our analysis of dysbiosis and T. vaginalis dysregulated miRNAs (SMAD4, UBE2I, STAT3, CDC41 and YWHAZ) remains to be investigated in the clinical context of T. vaginalis, BV and associated cancer and pregnancy complications." (PMID 36985125, 2023). "This conserved regulatory mechanism indicates that the regulation of UPR by SIRT7 via SMAD4 might also be similar in other types of cells and cancers." (PMID 36918544, 2023). "Moreover, AhR, JAB1 (Jun-activation domain binding protein) and SMAD4 interacted and formed a complex that induced ubiquitination of SMAD4 in AhR-overexpressing H1299 cancer cells." (PMID 37830596, 2023). "In this study, we focus on SMAD4 which has been reported to mediate OPN expression in cancer cells." (PMID 37670969, 2023). "For instance, genomic loss in the cancer cells of CDKN2A (encoding the cyclin-dependent kinase inhibitor p16INK4) and DPC4, encoding SMAD4, a central mediator of transforming growth factor (TGF)-β signaling, has been implicated in modifying the response to gemcitabine or 5-FU." (PMID 36831254, 2023). "SMAD4 is a crucial tumor suppressor gene and is frequently subverted in cancer progression." (PMID 36834681, 2023). "Thus, it is exciting to consider that SMAD4 expression would respond differently based on the environment, and how this influences cancer progression." (PMID 38136364, 2023). "A future RAB10 inhibitors could correspond to a new therapeutic solution for patients with cancer with SMAD4 deletion." (PMID 37377893, 2023). "Furthermore, thymoquinone worked effectively in combination with vitamin D3 and 5-fluorouracil and increased the expression of TGFβ and SMAD4 in chemical-induced cancer models." (PMID 35682990, 2022).
cancer (continued). "Thus, TGF-β-induced N-glycosylation changes can occur in a sex-determining region Y-related high-mobility group box 4–dependent and SMAD4-independent manner in the pancreatic PaTu-S cancer cell line." (PMID 35151689, 2022). "Also, loss of SMAD4 expression is reported in many solid tumors including CRC, leading to enhanced cancer cell proliferation." (PMID 35274815, 2022). "In summary, we establish that EMT can be implemented independently of SMAD4 in cancer cells." (PMID 34857888, 2022). "In light of the dual function of TGFβ signaling and SMAD4 in EMT processes, one could assume that mutations in TGFβ pathway components categorically preclude the occurrence of EMT in human cancer cells." (PMID 34857888, 2022). "Whether the HYAL-2/WWOX/SMAD4 signaling limits cancer and neurodegeneration in a balanced manner is unknown." (PMID 35883580, 2022). "However, the use of SMAD4 alternative promoters and transcripts they generate in the malignant cell remain unexplored as contributors to the SMAD4 deregulation in cancer." (PMID 35034624, 2022). "Further investigations are required to determine whether SMAD4-positive cancer cells, in which SMAD4 cytostatic and pro-apoptotic functions are active, also use SMAD2 and 3 as oncogenic factors." (PMID 36207615, 2022). "Finally, to evaluate SMAD4 on the residual cancer after chemotherapy and chemo-radiation therapy, we examined functional SMAD4 in resected specimens after neoadjuvant therapy." (PMID 36088360, 2022). "When cancer cells are transiently overexpressed with SMAD4, WWOX and HYAL-2, HA induces cell death." (PMID 35883580, 2022). "SMAD4 mutations show a higher prevalence in BRAF/PIK3CA double mutant cancers of the TCGA cohort but not in cancers with BRAF mutations without PIK3CA mutations." (PMID 36079062, 2022). "Although vital roles of the mothers against decapentaplegic homolog 4 (also called ‘SMAD4’) have been discussed in different cancers and stem cell‐related studies, there are a few reviews summarizing the roles of this protein in the skeletal development and bone homeostasis." (PMID 34841647, 2022). "To determine the impact of SMAD4 loss on additional immune cell processes, particularly those related to cancer immunotherapy, we next explored the relationship between SMAD4 and PD-L1 in vitro, first evaluating the basal expression of PD-L1 in a variety of established PDAC cell lines." (PMID 35155243, 2022). "KRAS G12R mutated cancers with co-occurring PI3K pathway mutations vs. those without PI3K pathway genetic alterations harbored significantly more SMAD4 gene defects (83.3% vs. 11.8%, P = .0034)." (PMID 36124727, 2022). "It is therefore widely assumed that SMAD4-mutant (SMAD4mut) cancer cells are unable to undergo EMT." (PMID 34857888, 2022). "As a cancer suppressor, Smad4 is involved in Wnt-Kras-mediated inhibition of colorectal cancer." (PMID 35847921, 2022). "Besides SMAD4 and DCC, this region encloses known cancer-related genes that were significantly associated with a higher relapse probability of early-stage primary tumors, namely SMAD2 and BCL2." (PMID 36085309, 2022).
cancer (continued). "For example, mutations in the SMAD4 and TGFβ type II receptor (TGFBRII) genes may make cancer cells resistant to TGFβ’s antimitogenic activity." (PMID 35743003, 2022). "Oncogenic role of SMAD4: SMAD4 has been shown to play oncogenic role in different cancers." (PMID 33511320, 2021). "In contrast, other studies have indicated that Smad4 inhibits cancer progression." (PMID 34383767, 2021). "However, considering all results, including sphere-forming, clonogenicity potential, and invasiveness of cancer cells, our data suggest that SMAD4 inhibition reduces EMT‐induced renal CSC properties." (PMID 34012911, 2021). "The biologic effects of SMAD4 in cancer are mediated through TGF‐β signaling." (PMID 34002944, 2021). "We also confirmed the common occurrence of deleterious mutations in SMAD4 and further characterized the specific hotspot mutations in SMAD4, SMAD2 and DICER1, the last group of which were previously reported mostly in childhood cancers." (PMID 33406242, 2021). "The discrepancy between these 2 studies may be due to different reagents, such as a primary anti-SMAD4 antibodies, and occurrence of cancer-related deaths in RCC patients." (PMID 34012911, 2021). "On the other hand, in advanced pancreatic ductal adenocarcinomas (PDAC), intact TGF-β/SMAD4 pathway facilitates cancer progression; in advanced prostate cancer, bone-borne TGF-β induces osteoclastogenesis and bone metastasis by activating chemokine (C-X-C motif) receptor 4 (CXCR4)." (PMID 34917620, 2021). "However, later-stage cancers can become desensitized to the anti-cancer effects of SMAD4 and the SMAD2/3/4 complex." (PMID 34572031, 2021). "This revealed that the cancer resistance induced by SMAD4 loss was not dependent on the type of chemo-drugs." (PMID 34048444, 2021). "Comparing the mutation status of cancer critical genes in PUMC-CRC1 with that in 19 commonly-used CRC cell lines, PUMC-CRC1 was a unique cell line with APC (p.T1493fs), KRAS (p.G12V) and SMAD4 (p.V506A) mutations, which enriches the diversity of CRC cell lines." (PMID 34162944, 2021). "The alteration of the TGF-β signaling pathway by the COL11A1 gene indicates that the SMAD4 alteration frequency of 15.5% might drive the formation of cancer." (PMID 33597969, 2021). "SMAD4 mutations are not observed in most noninvasive MCNs, but protein expression is frequently lost in invasive cancers arising from MCNs." (PMID 35008235, 2021). "This was mainly based on the exploring that the inhibition of SMAD4 simultaneously with the decreased TGFβ1 reduces the formation of highly invasive cancer spheres in PCs, decreases clonogenicity, and invasiveness of cancer cells and leads to increase in EMT-related properties." (PMID 34012911, 2021). "In the subgroup analysis, cancer type, drug type, sample size and antibody brand did not affect the significance of association between loss of SMAD4 expression and drug resistance." (PMID 34048444, 2021). "In the current study, we demonstrate that TGF-β signaling with a preserved SMAD4 function can contribute to cancer through associations with negative pathway regulators." (PMID 34070531, 2021). "Depletion of Smad4 from T cells in mice leads to epithelial carcinomas in the gut." (PMID 34966673, 2021). "Other factors that regulate Smad4 expression are not well understood, though Smad4 drives the development of activated T cells that participate in immune surveillance to protect the host from cancers, including CRC." (PMID 33424832, 2020).
cancer (continued). "The deletion of SMAD4 (both heterozygous and homozygous deletion) was initially discovered in pancreatic duct adenocarcinoma, followed by its detection in other cancers, like gastric, prostate, or colorectal cancers, albeit at reduced frequency compared to PDAC." (PMID 32781778, 2020). "Why Smad4 is downregulated during cancer is unclear, but it is not likely due to mutation, as only 8.6% of cases in a cohort of 744 primary sporadic CRC patients had Smad4 mutations." (PMID 33424832, 2020). "We investigated whether synthetic Zfra4-10 or WWOX7-21 peptide-mediated cancer suppression occurs via the Hyal-2/WWOX/SMAD4 signaling for cytotoxic memory Z cell activation in the spleen." (PMID 32764489, 2020). "Oppositely, the over-expression of SMAD4 enhances apoptosis and inhibits cancer cell proliferation." (PMID 32244895, 2020). "Therefore, this study provides valuable information for developing a novel strategy for cancer-targeting gene-virotherapy and advances our understanding of the critical role of Smad4 in gene therapy of CRC." (PMID 33322272, 2020). "Analysis of 523 cancer-relevant genes and of immune cells infiltration in primary and metastatic tissues revealed atypical genomic trajectories (TMB decrease, KRAS and SMAD4 regressive mutations), specific genetic events (ERBB2 point mutations) and scarce T-cell infiltration." (PMID 32332709, 2020). "SMAD4 was low (50%, 40/80) in the normal pancreas and mainly low (73.8%, 59/80) in cancer." (PMID 32565799, 2020). "The signaling pathway TGFβ/SMAD4 controls transduction from plasma membrane to nucleus and affects a large number of processes, such as proliferation, differentiation, apoptosis, migration, and cancer initiation and progression." (PMID 32781778, 2020). "In addition, Smad4 staining of the majority of cancer cells significantly correlated to cancer-specific death." (PMID 31238579, 2019). "High Smad4 was found in 53.1% (51/96) pTa, 49.0% (95/194) pT1, and 31.8% (35/110) pT2 cancers." (PMID 31238579, 2019). "To further understand how DEGs were regulated, we analysed transcription factor (TF) binding using Enrichr and observed that DEGs were enriched for targets of TFs associated with self-renewal and cancer stem cell function (SUZ12, SOX2, REST, EZH2, SMAD4 and NANOG)." (PMID 31014368, 2019). "Additionally, evidence from recent studies has shown that cancer development can be affected by mutations in the TGFβII receptor (TGFBR2), SMAD4, and activin receptor 2A (ACVR2A)." (PMID 31906017, 2019). "For example, WWOX7-21 peptide may physically bind the membrane Hyal-2/WWOX complex to undergo nuclear relocation, together with Smad4, for blocking cancer cell growth." (PMID 31752354, 2019). "Based on this information, we speculate that SMAD4 Y353C may induce the malignant transformation and metastasis of cancer cells by regulating CSCs, which should be further investigated in the future." (PMID 31684910, 2019). "Deregulation of this miRNA is important for GC progression because it promotes cell proliferation by down-regulating the expression of CDKN1B (p27kip1) tumor suppressor and invasion and epithelial to mesenchymal transition of cancer stem cells by down-regulating the expression of SMAD4 in GC." (PMID 31275362, 2019). "Therefore, there are many target genes regulated by SMAD4, indicating that several changes in cancer cells happen when R-SMAD-SMAD4 complexes are disrupted." (PMID 31756952, 2019).